ADGRV1 (adhesion G protein-coupled receptor V1)
Diseases named in the same sentence as ADGRV1 in open-access papers (continued):
Sharing a sentence is not in itself a finding about the gene and the disease.
epilepsy (continued). "ADGRV1 is potentially associated with FS-related epilepsy as a susceptibility gene." (PMID 35813073, 2022). "ADGRV1 variants were identified in 8.91% of the cases and listed as the second, suggesting that ADGRV1 was one of the candidate genes associated with FS or FS-related epilepsy." (PMID 35813073, 2022). "More recently, a few studies suggested that ADGRV1 gene could be a susceptibility gene in different types of epilepsy like focal epilepsy, epileptic encephalopathy, or myoclonic epilepsies." (PMID 34744978, 2021). "In addition, the p.Glu3215Lys variant in ADGRV1 was reported in a patient with focal epilepsy and sudden unexpected death in epilepsy (SUDEP)." (PMID 34744978, 2021). "In addition, adhesion G protein-coupled receptor V1 (ADGRV1) is potentially associated with FS-related epilepsy as a susceptibility gene, encoding a very large G protein-coupled receptor-1 (VLGR1), which is localized at synaptic junctions and cooperatively regulates synaptic function." (PMID 37305674, 2023). "While the USH defects are attributed to the loss of fiber links between membranes formed by the extracellular domain of ADGRV1, the pathomechanisms leading to epilepsy remain elusive to date." (PMID 42002803, 2026). "There is evidence that SULT1C4, NAALAD2, and ADGRV1 participate in neurotransmitter regulation, glutamate dysregulation in schizophrenia, and epilepsy and audiovisual disorders." (PMID 40428414, 2025). "Genes potentially associated with FS-related epilepsy include SCN1A, ADGRV1, SCN1B, SCN9A, GABRG2, GABRD, and CPA6." (PMID 35813073, 2022). "A correlation between the severity of the epilepsy phenotype and ADGRV1 impairment was also suggested in this study." (PMID 35813073, 2022). "A key remaining question is how ADGRV1 variants can lead to such diverse disorders as Usher type IIC syndrome and epilepsy." (PMID 34744978, 2021). "Among the 22 shared heterozygous prioritized filtered variants, we identified variants in the ADGRV1 and KCN1P1 gene, already flagged as related to epilepsy, making them the best candidates by function." (PMID 34744978, 2021). "Although there is growing evidence that dysfunctions of primary cilia are associated with epilepsy, it is not clear to what extent these are caused by defects in ADGRV1." (PMID 40103630, 2025). "Up to now, four studies have suggested the involvement of ADGRV1 in human epilepsy." (PMID 34744978, 2021). "A study by our group that included 20 epilepsy patients with personal or family history of heart rhythm disturbance/cardiac arrhythmia/sudden death identified four missense variants in epilepsy genes CDKL5, CNTNAP2, GRIN2A, and ADGRV1, with complete segregation within the family." (PMID 31018519, 2019). "The variant identified in the ADGRV1 gene of ID#7 is present in the non-affected mother, and no family history of epilepsy or LQTS is known." (PMID 29261713, 2017). "Dysfunction or absence of ADGRV1 from primary cilia may underlay the pathophysiology of human Usher syndrome type 2 and specific forms of epilepsy caused by mutations in ADGRV1." (PMID 40103630, 2025). "However, the severe phenotype of epilepsy had not been observed in the USH2 cases that carried ADGRV1 variants of severe genetic impairment." (PMID 35813073, 2022). "In this study, we screened epilepsy-related genes in 101 unrelated cases with FS or epilepsy with antecedent FS (EFS+) using a targeted sequencing approach and identified eight heterozygous variants and a pair of compound heterozygous variants of ADGRV1 in nine unrelated cases." (PMID 35813073, 2022). "The deletion of ADGRV1 could be responsible for the epilepsy phenotype." (PMID 34621295, 2021). "In 8 patients, one or more epilepsy genes, GRIN2A, TET3, SCN1A, SCN8A, ADGRV1, DLG4, and SLC12A5, were found, and 12 patients had no genetic mutations." (PMID 38813507, 2023).
Usher syndrome type 2 (17 papers, 2012 to 2025). "Numerous mutations in the human ADGRV1 gene are causative for the human Usher syndrome type 2 (USH2C)." (PMID 40103630, 2025). "Mutations in the GPR98 gene, also known as adhesion G protein-coupled receptor V1 (ADGRV1) are associated with Usher syndrome type 2." (PMID 37893030, 2023). "In contrast to USH2A, variants in ADGRV1 are a minor cause of Usher syndrome type 2, and the associated phenotype is less known." (PMID 34638692, 2021). "Variants in ADGRV1 gene are associated with audio-visual disorders, typically Usher syndrome type 2 (USH2), which is characterized by moderate-to-severe congenital sensorineural hearing loss and postnatal retinitis pigmentosa." (PMID 35813073, 2022). "A noteworthy feature of this study is represented by a peculiar enrichment in patients affected by Usher syndrome type 2, carrying biallelic variants in the USH2A (4/7) and ADGRV1 (3/7) genes." (PMID 36979683, 2023). "The prevalence of Usher syndrome type 2 patients in our cohort is slightly higher than expected and, to date, no published study has so far analysed the prevalence of USH2A and ADGRV1 pathogenic variant carriers in the Italian population." (PMID 36979683, 2023). "Additionally, a peculiar finding of this study is represented by the overall identification of seven patients (7/102—6.9%) affected by Usher syndrome type 2 due to biallelic variants in the USH2A (4/7) and ADGRV1 (3/7) genes." (PMID 36979683, 2023).
deafness (15 papers, 2013 to 2023). An inherited or acquired condition characterized by the complete loss of the ability to hear from one or both ears. "Taken together, these data suggest that Adgrv1 Y6236fsX1 mutant mice are profoundly deaf and thus serve as a useful animal model for studying ADGRV1 Y6244fsX1 mutation‐associated deafness." (PMID 37066759, 2023). "In the current study, we generated Adgrv1 mutant mice to mimic the deafness‐associated human mutation ADGRV1 Y6244fsX1." (PMID 37066759, 2023). "Notably, the immunostaining results revealed that ADGRV1 Y6236fsX1 is targeted to the apical surface of hair cells rather than at the base of stereocilia, suggesting that this deafness‐associated mutation affects the localization of ADGRV1 in hair cells." (PMID 37066759, 2023). "There were 18 genes linked only to Metabolic hearing loss (including four deafness genes: DMD, DUOX2, CELSR1 and ELMO3) and 54 genes linked only to Sensory hearing loss (including four deafness genes: ARHGAP21, LMO7, UBE3B and ADGRV1)." (PMID 38011198, 2023). "In this study, 48.5% (16/33) families were detected the pathogenic variants in eight known deafness genes, including 10 novel variants identified in TMPRSS3 (MIM 605551), MYO15A (MIM 602666), TMC1 (MIM 606706), ADGRV1 (MIM 602851), and PTPRQ (MIM 603317)." (PMID 31379920, 2019). "We found that A64D and R223H on WHRN, although not affecting binding to USH2A or ADGRV1, cause deafness by disturbing WHRN dimerization and disrupting phase separation of USH2 condensates." (PMID 36964137, 2023). "The deafness‐related Adgrv1 Y6236fsX1 mutant, which remains mostly structurally intact but causes disruption of the ALC and alters downstream Gi signaling, serves as a valuable model to probe the dynamic regulation of the ALC and the role of ADGRV1‐mediated signaling." (PMID 37066759, 2023). "The known deafness genes with variants detected in this study were GJB2 (MIM 121011; 21.2%), TMPRSS3 (MIM 605551; 6.1%), MYO15A (MIM 602666; 6.1%), TMC1 (MIM 606706; 3%), ADGRV1 (MIM 602851; 3%), PTPRQ (MIM 603317; 3%), SLC26A4 (MIM 605646; 3%), and OTOF (MIM 603681; 3%)." (PMID 31379920, 2019).
hearing loss (13 papers, 2018 to 2026). "Furthermore, there are links between missense mutations in EMR2/ADGRE2 and defects in VLGR1/ADGRV1 with familial vibratory urticaria and hearing loss, respectively." (PMID 36406261, 2022). "This is consistent with previous reports of ADGRV1 pathogenic variants associated with early onset of hearing loss with delayed visual impairment, most of which are located in the calx-β motif, and the ADGRV1 c.17062C > T lies downstream (3′) to this calx-β motif." (PMID 31046701, 2019). "Similarly, we find that two sisters with hereditary hearing loss, the product of a second cousin union, are homozygous for a nonsense pathogenic variant in ADGRV1 (c.17062C > T, p.Arg5688*)." (PMID 31046701, 2019). "USH2A, ADGRV1, and WHRN are the three known USH2 causative genes, which are also linked to isolated retinal degeneration and hearing loss." (PMID 41654259, 2026). "Ironically, both ADGRV1 and GRXCR1 are associated with auditory hair development and mutations are linked to hearing loss." (PMID 29670642, 2018).
retinitis pigmentosa (9 papers, 2012 to 2025). Retinitis pigmentosa (RP) is an inherited retinal dystrophy leading to progressive loss of the photoreceptors and retinal pigment epithelium and resulting in blindness usually after several decades. "This study demonstrates a structure-guided exon excision strategy for the future treatment of ADGRV1-associated retinitis pigmentosa." (PMID 41036464, 2025). "ADGRV1 loss of function variants have been reported to cause the rare form of AR Usher syndrome Type IIC (OMIM #605472) characterized by retinitis pigmentosa and mild-to-moderate sensorineural hearing loss." (PMID 34744978, 2021). "Given the lack of treatment options for ADGRV1-associated retinitis pigmentosa (RP), we evaluated exon excision as a potential therapeutic strategy." (PMID 41036464, 2025). "Worldwide, around 40,000 people progressively lose their eyesight as a consequence of retinitis pigmentosa (RP) caused by pathogenic variants in the ADGRV1 gene, for which currently no treatment options exist." (PMID 37371069, 2023).
retinal degeneration (7 papers, 2019 to 2026). Degeneration of the retina. "Defects in several of these ciliary DEGs have been associated with USH (Cep250 (atypical USH), Pcdh15 (USH1F) or other retinal ciliopathies Fam164a (RP28) leading to retinal degenerations as seen in USH2C patients with pathogenic variants in the ADGRV1 gene." (PMID 40103630, 2025). "There is evidence that prolonged periods of degradation pathway overload are likely to affect protein homeostasis unbalancing proteostasis associated with inherited retinal degenerations which possibly is also the case in ADGRV1-related diseases." (PMID 40103630, 2025). "Lacking a progressive phenotype, the restoration of the USH2 protein complex at the periciliary region, and normal rhodopsin trafficking, provide valuable biomarkers to evaluate future therapeutic strategies for ADGRV1-associated retinal degeneration in the adgrv1rmc22 zebrafish." (PMID 37371069, 2023). "Mutations in ADGRV1 may result in Usher syndrome 2C, which is characterized by congenital moderate‐to‐severe hearing loss, retinal degeneration in the second decade of life or later, and normal vestibular function (Zhang, Wang, Liu, Liu, & Jiang, 2018)." (PMID 32048449, 2020). "ADGRV1, a gene that is crucial for the development of hair cells, can result in Usher syndrome 2C, which is characterized by congenital moderate-to-severe hearing loss, retinal degeneration in the second decade of life or later, and normal vestibular function." (PMID 31379920, 2019). "The significant increase in the number of photoreceptors with the aberrant localization of rhodopsin in the retinal sections of adgrv1rmc22 larvae indeed supports the notion that defective ciliary protein transport may lie at the origin of ADGRV1-associated retinal degeneration." (PMID 37371069, 2023). "Individuals with ADGRV1-related USH II often present with a clinical picture that closely resembles USH2A-associated cases in terms of both hearing loss and retinal degeneration." (PMID 40149483, 2025).
melanoma (5 papers, 2018 to 2023). A malignant, usually aggressive tumor composed of atypical, neoplastic melanocytes. "The top 10 mutated genes in melanoma were TTN (72%), MUC16 (67%), DNAH5 (49%), PCLO (44%), LRP1B (38%), ANK3 (32%), DNAH7 (32%), ADGRV1 (35%), RP1 (33%), and BRAF (51%)." (PMID 33758620, 2021). "The top 10 mutated genes in 467 melanoma patients are TTN (72%), MUC16 (67%), BRAF (51%), DNAH5 (49%), PCLO (44%), LRP1B (38%), ADGRV1 (35%), RP1 (33%), ANK3 (32%), DNAH7 (32%)." (PMID 33072607, 2020).
retinal disease (4 papers, 2015 to 2022). "The present study includes the largest cohort of ADGRV1 patients published to date (n = 18) and provides a detailed overview of the functional and structural parameters of the associated retinal disease." (PMID 34638692, 2021).
Bardet-Biedl syndrome (3 papers, 2023 to 2026). A ciliopathy with multisystem involvement. "The ADGRV1 intracellular bait pulled down proteins involved in actin-based cell projections, the chaperone-containing TCP-1 complex, and the Bardet-Biedl syndrome complex." (PMID 41654259, 2026).
breast carcinoma (3 papers, 2015 to 2023). "GPR98, a.k.a ADGRV1, has a reported mutation frequency of 2% in the TCGA breast cancer cohort and is one among the frequently mutated GPCR in TCGA cancers." (PMID 37454130, 2023). "Cell-type-specific TWAS using MiXcan identified five genes (ADGRV1, ZNF703, TMEM245, CDYL2, and PSG4), including three novel breast cancer susceptibility genes, that were not identified by either PrediXcan or PredictDB." (PMID 36690614, 2023). "Six of these genes (MRPS30, SETD9, ADGRV1, ZNF703, PRR33, and PSG4) showed different directions of association with breast cancer in epithelial vs. stromal (nonepithelial) cells." (PMID 36690614, 2023).
focal epilepsy (3 papers, 2017 to 2021). A seizure caused by a localized disorder. "Of the three APEs with the ADGRV1 p.His1859Arg variant, two were diagnosed with focal epilepsy and one with generalized epilepsy." (PMID 31875159, 2019). "ID#7 is a 16-year-old boy affected by focal epilepsy and LQTS and carrying a rare genetic variant in ADGRV1 that was harboured by his healthy mother (I:2)." (PMID 29261713, 2017).
Seizure (3 papers, 2019 to 2022). A seizure is an intermittent abnormality of nervous system physiology characterized by a transient occurrence of signs and/or symptoms due to abnormal excessive or synchronous neuronal activity in the brain. "In our study, three APEs with the ADGRV1 heterozygous variant (p.His1859Arg) had either focal or generalized epilepsy, which might be plausible if a focal myoclonic seizure was confused with a focal motor seizure, as is occasionally the case in outpatient clinics." (PMID 31875159, 2019).
ciliopathies (2 papers, 2024 to 2025). "In humans, mutations in the ADGRV1 gene causes Usher syndrome type IIC, a ciliopathy characterized by hearing loss and visual impairment." (PMID 38715151, 2024).
cutaneous melanoma (2 papers, 2022). A primary melanoma arising from atypical melanocytes in the skin. "Among them, PKHD1L1, LRP1B, ADGRV1 and DNAH10 were hypomethylated in UV-mutant compared with non UV-mutant cutaneous melanoma patients in BCH." (PMID 35840550, 2022).
familial febrile seizure 4 (2 papers, 2021 to 2022). "ADGRV1 mutation has been seen previously associated with familial febrile seizure 4, which is a febrile disease." (PMID 35096640, 2021).
ovarian carcinoma (2 papers, 2022 to 2025). A malignant neoplasm originating from the surface ovarian epithelium. "The mutation rates of ADGRV1 (Adhesion G Protein-Coupled Receptor V1) were the highest among seven genes in both GC and ovarian cancer, with 13.45% (55 out of 409) and 2.66% (19 out of 705) of samples, respectively." (PMID 40860157, 2025). "For the first time, we report the immune‐related mutations of ZNF462, ADGRV1 and FLG2 in ovarian cancer." (PMID 35735060, 2022).
retinal ciliopathy (2 papers, 2023 to 2025). "Moreover, due to the presence of defects in photoreceptor cilia in cell and animal models for USH, evidence has been accumulating in recent years that USH is considered a retinal ciliopathy which is consistent with the ciliary association of CIB2 and ADGRV1 described here." (PMID 37427378, 2023).
Anxiety (1 paper, 2019). Intense feelings of nervousness, tension, or panic often arise in response to interpersonal stresses. "Many of these disorders are among what we have identified for this study in the top ten diseases significantly enriched by the ADGRV1 co-expressed genes, such as fatigue, infertility, anxiety or panic disorder." (PMID 31792237, 2019).
autoimmune disease (1 paper, 2021). A disorder resulting from loss of function or tissue destruction of an organ or multiple organs, arising from humoral or cellular immune responses of the individual to their own tissue constituents. "Since the patient in our study also presented with recurrent fever without evidence of infection or common autoimmune disease, we propose that the new mutation in ADGRV1 may have an impact on the occurrence of febrile disease in this patient." (PMID 35096640, 2021).
depression (1 paper, 2019). "Moreover, GPCRs (including ADGRA1, ADGRV1, CELSR2, and S1PR5) previously reported to be implicated in the physiopathology and pharmacology of depression were also significantly altered." (PMID 30983951, 2019).
heart failure (1 paper, 2019). Inability of the heart to pump blood at an adequate rate to meet tissue metabolic requirements. "The ADGRV1 expression in heart supports a previous study of sexually dimorphic ADGRV1 expression in patients with non-ischemic human heart failure, in which ADGRV1 expression was lower in men than women, the same effect direction to what we found in the GTEx transcriptome." (PMID 31792237, 2019).
myoclonic seizures (1 paper, 2019). "ADGRV1 haploinsufficiency may be an important contributor to the development of genetic epilepsies, particularly those with myoclonic seizures." (PMID 31875159, 2019).
temporal lobe epilepsy (1 paper, 2023). A localization-related (focal) form of epilepsy characterized by recurrent seizures that arise from foci within the temporal lobe, most commonly from its mesial aspect. "We hypothesized that the discovered missense variant might lead to dysfunction of ADGRV1 protein, contributing to the unique phenotypes, temporal lobe epilepsy and ictal asystole observed in our patient." (PMID 40217298, 2023).
visual disorders (1 paper, 2022). "On the contrary, most of the currently reported ADGRV1 variants have been identified in audio-visual disorders." (PMID 35813073, 2022). "Previously reported ADGRV1 variants that were associated with audio-visual disorders were mostly biallelic/destructive variants, which were significantly more frequent in the severe phenotype of audio-visual disorders (Usher syndrome 2) than in other mild phenotypes." (PMID 35813073, 2022). "ADGRV1 mutations are associated with audio-visual disorders." (PMID 35813073, 2022).
cancer (10 papers, 2014 to 2023). A tumor composed of atypical neoplastic, often pleomorphic cells that invade other tissues. "Variants in ADGRV1, which encodes adhesion G protein-coupled receptor 1, were potentially heterozygous, and the implication of this protein in cancer progression is unclear." (PMID 32575483, 2020).
infection (3 papers, 2021 to 2024). The state of being infected such as from the introduction of a foreign agent such as serum, vaccine, antigenic substance or organism. "In Caco-2 cells, no increase in mRNA expression of ADGRB3/BAI3, ADGRG7/GPR128 and ADGRV1/GPR98 was detected even 48 h after infection, thus confirming our results after 12 h post infection." (PMID 38786015, 2024). "In Calu-3 cells, the relative mRNA expression upon infection with infectious SARS-CoV-2 exhibited a pronounced increase in the cases of ADGRD1/GPR133 and ADGRG7/GPR128, a small increase in the case of ADGRB3/BAI3 and a negligible change in that of ADGRV1/GPR98 mRNA levels after 24 and 48 h." (PMID 38786015, 2024).